MIR513B (microRNA 513b)
Synonyms: hsa-mir-513b; MIRN513B
Gene: MicroRNA gene on chromosome X (147,199,044 to 147,199,127, reverse strand). Ensembl gene ENSG00000207871.
Homologues: Orthologues: macaque mml-mir-513b-2 (92% identical), macaque mml-mir-513a-2 (90% identical), macaque mml-mir-513b-1 (90% identical), macaque mml-mir-513a-1 (89% identical), macaque mml-mir-513a-3 (88% identical), dog MIR507B (71% identical), rabbit ocu-mir-506 (40% identical), mouse Mir511 (36% identical). Paralogues in human: MIR513A2 (93% identical), MIR506 (68% identical), MIR507 (65% identical), MIR514A1 (60% identical), MIR514B (60% identical), MIR509-1 (58% identical), MIR514A2 (58% identical), MIR514A3 (58% identical), MIR509-3 (51% identical).